IRF2 (interferon regulatory factor 2)
Diseases named in the same sentence as IRF2 in open-access papers (continued):
Sharing a sentence is not in itself a finding about the gene and the disease.
glioma (5 papers, 2021 to 2024). A benign or malignant brain and spinal cord tumor that arises from glial cells (astrocytes, oligodendrocytes, ependymal cells). "A convey revealing the relationship between ferroptosis-related genes (FRGs) and gliomas indicated that interferon regulatory factor 2 (IRF2) was positively associated with glioma grade and contributed to gliomas, potentially by maintaining low ACSL4 level and high xCT/GPX4 level." (PMID 39309434, 2024). "Oppositely, enhanced IRF2 in gliomas may interfere with SLC7A11 and GPX4 to extinguish ferroptosis." (PMID 39309434, 2024). "We found that IRF1, IRF2, IRF5, IRF7, IRF8, and IRF9 were upregulated in glioma compared with normal tissue." (PMID 33902005, 2021). "We found that IRF1, IRF2, IRF5, IRF8 and IRF9 were significantly upregulated in glioma compared to normal brain tissue." (PMID 33902005, 2021). "We found that 4 of 26 predicted TFs (IRF1, IRF2, CEBPB, and PRDM1) were upregulated at the mRNA level in MR1 high gliomas." (PMID 33948562, 2021). "In summary, this study showed that IRF1, IRF2, IRF5, IRF8, and IRF9 mRNA levels were increased in glioma compared to normal tissue." (PMID 33902005, 2021). "Of these, IRF1, IRF2, and PRDM1 were upregulated in all grades of glioma, while CEBPB was just upregulated in grade III and combined." (PMID 33948562, 2021). "Overall survival curves indicated that glioma patients with lower IRF1 (p = 4.42E-33), IRF2 (p = 2.22E-16), IRF3 (p = 1.43E-15), IRF4 (p = 0.004), IRF5 p = 5.84E-12), IRF7 (p = 6.85E-28), IRF8 (p = 0.001), and IRF9 (p = 0.000) transcript levels had significantly longer overall survival times." (PMID 33902005, 2021). "Collectively, these results indicate that IRF family members, including IRF1, IRF2, IRF5, IRF8 and IRF9, may serve as prognostic biomarkers and indicators of immune status in glioma patients." (PMID 33902005, 2021). "Among the 260 grade II, 267 grade III, and 173 grade IV glioma patients, significant correlations were observed between IRF1 (p = 8.00E-61), IRF2 (p = 6.80E-18), IRF3 (p = 1.70E-23), IRF5 (p = 2.30E-08), IRF7 (p = 1.90E-29), IRF8 (p = 0.029), IRF9 (p = 4.80E-05) expression and pathological grade." (PMID 33902005, 2021). "Of these, IRF1 (low grade n = 4, high grade n = 4), IRF2 (low grade n = 8, high grade n = 16), and CEBPB (low grade n = 2, high grade n = 7) also showed different and disperse levels of staining in histology (non-detected; +, low; ++, medium; +++, high) from THPA among high- and low-grade gliomas." (PMID 33948562, 2021).
leukemia (5 papers, 2016 to 2024). A malignant (clonal) hematologic disorder, involving hematopoietic stem cells and characterized by the presence of primitive or atypical myeloid or lymphoid cells in the bone marrow and the blood. "BM-MSCs-Exo directly target the IRF2 gene by secreting miR-222-3p, negatively regulating the IRF2/INPP4B pathway in THP-1 cells, leading to the suppression of leukaemia cell proliferation, the promotion of apoptosis, and the prevention of leukaemia progression." (PMID 39416732, 2024).
testicular embryonal carcinoma (5 papers, 2019 to 2022). A malignant germ cell neoplasm arising from the testis.
lymph node metastasis (4 papers, 2017 to 2023). "Enhanced IRF-2 serum levels in CRC patients with lymph node metastasis present themselves as a novel biomarker for metastasis." (PMID 36901813, 2023). "Univariate analysis showed that TNM stage, tumor infiltration, distant metastasis, lymph node metastasis, preoperative serum CEA and CA19-9 level together with IRF-2 expression were significantly associated with overall survival." (PMID 28465494, 2017). "Considering that the invasive depth, lymph node metastasis, and distant metastases were included in the TNM stage, we only included tumor size, TNM stage, and expression of IRF-2 in the multivariate analysis." (PMID 35115027, 2022).
nasopharyngeal carcinoma (4 papers, 2021 to 2023). A carcinoma arising from the nasopharyngeal epithelium. "IRF2 is reported to facilitate cell proliferation and suppress apoptosis of nasopharyngeal carcinoma through AKT pathway." (PMID 37621743, 2023). "IRF-2 promotes malignant behaviors including glycolysis, cell proliferation, and cell cycle arrest in nasopharyngeal cancer; IRF-2 can also induce cell apoptosis and repress cell proliferation and migration ability in non-small cell lung cancer." (PMID 35115027, 2022). "In nasopharyngeal carcinoma cells, super-enhancers are enriched of BRD4, NF-κB, IRF1 and IRF2 transcription factors at the loci of critical oncogenes such as ETV6, high expression of which in human nasopharyngeal carcinoma tissues is correlated with poor patient prognosis." (PMID 38135679, 2023).
osteosarcoma (4 papers, 2020 to 2022). A usually aggressive malignant bone-forming mesenchymal neoplasm, predominantly affecting adolescents and young adults. "The tumor suppressor genes PTEN and IRF2 have also been reported as direct targets of miR-18a in osteosarcoma." (PMID 33392094, 2020).
rectal cancer (4 papers, 2014 to 2019). A primary or metastatic malignant neoplasm that affects the rectum. "Several cytokines, including interleukins and interferons, and other mediators of inflammation were associated with both colon (INFGR1, IL6, IRF2, NFκB1A, TLR2) and rectal cancer survival (IL1A and IL3), as was suppressor of cytokine signaling (SOCS1)." (PMID 25541970, 2014). "Seven genes (IL2RA, IL8RA, IL8RB, IRF2, RAF1, RUNX3, and SEPX1) were significantly associated with rectal cancer (PARTP<0.05)." (PMID 25541970, 2014). "In particular, the authors demonstrated that the IRF2 mutational status is associated with both colon and rectal cancer, whereas mutations in other genes involved in IFN signaling pathway were uniquely associated with colon (IFN-γ and IRF3) or rectal cancer (IFNGR1, IFNGR2, IRF4, IRF6, and IRF8)." (PMID 28798748, 2017).
asthma (3 papers, 2023 to 2025). "Notably, IRF2 is required for induction of TLR3 and other interferon-inducible genes critical to mount antiviral responses and severe viral respiratory infection in early life is a risk factor for asthma development in later childhood." (PMID 38974097, 2024).
autoimmune disease (3 papers, 2022 to 2025). A disorder resulting from loss of function or tissue destruction of an organ or multiple organs, arising from humoral or cellular immune responses of the individual to their own tissue constituents. "For instance, IRF2 (Interferon Regulatory Factor 2) plays a critical role in modulating interferon signaling and immune responses, and its dysregulation has been associated with autoimmune diseases." (PMID 40740938, 2025). "Moreover, IRF2 silencing significantly attenuated canonical and noncanonical inflammasome-mediated pyroptosis and IL-1β release, suggesting that IRF2 is a reliable drug target for the treatment of autoimmune disease." (PMID 35693810, 2022).
ductal carcinoma in situ (3 papers, 2011 to 2018). "Furthermore, high-grade ductal carcinoma in situ (DCIS) or node-positive invasive ductal cancers were less likely to express IRF1 and were much more likely to have higher oncogenic IRF2 protein than normal." (PMID 22295238, 2011). "In one retrospective study, IRF-1 but not IRF-2 was found to be expressed in normal breast tissue, whereas levels of the former were shown to be lower and those of the latter higher in high-grade ductal carcinoma in situ (DCIS) and lymph node-positive invasive ductal cancer." (PMID 29599126, 2018).
esophageal squamous cell carcinoma (3 papers, 2018 to 2022). Esophageal squamous cell carcinoma (ESCC) is a type of esophageal carcinoma (EC) that can affect any part of the esophagus, but is usually located in the upper or middle third. "Wang and colleagues have further investigated the part played by IRFs in esophageal malignancies by measuring patterns of IRF-1 and IRF-2 protein expression in esophageal squamous cell carcinoma (ESCC) and correlating them with the clinical features of this disease." (PMID 29599126, 2018). "IRF2 expression was increased in esophageal squamous cell carcinomas (ESCC) compared with matched normal esophageal tissues." (PMID 35012444, 2022). "Similarly, the interferon regulatory factor 2 (IRF2) gene, was reported to increase the tumorigenicity of esophageal squamous cell carcinoma when overexpressed." (PMID 31892232, 2019).
HIV-1 infection (3 papers, 2011 to 2023). The type species of lentivirus and the etiologic agent of acquired immunodeficiency syndrome (AIDS). "IRF1 and IRF2 are ubiquitously expressed in cells, although they can be upregulated by type I IFNs and, in the case of IRF1, by TLR signaling and HIV-1 infection, illustrating how HIV-1 can coopt the antiviral IFN response to augment its own replication." (PMID 33472928, 2021). "The IRF2 gene is a cis-regulatory target of the lncRNA RP11-290F5.1, suggesting that this lncRNA may play a regulatory role in the process of HIV-1 infection." (PMID 38110484, 2023).
liver cancer (3 papers, 2017 to 2023). An epithelial or non-epithelial malignant neoplasm that arises from the liver. "IRF2 modulates cell survival of liver cancer via regulating β-catenin." (PMID 37621743, 2023). "In liver cancer, IRF2 can inactivate the STAT3 signaling pathway." (PMID 34022918, 2021). "DAPK1 expression was positively correlated with IRF2, IL7R, PCOLCE and ZBTB16, and negatively correlated with SLC16A3 in both liver cancer datasets." (PMID 28740751, 2017).
medulloblastoma (3 papers, 1998 to 2021). A malignant, invasive embryonal neoplasm arising from the cerebellum. "The persistent interferon regulatory factor 2 (IRF2) and IRF2-binding protein 2 (IRF2BP2) overexpression lasts for up to 48 hours after IFN-γ exposure in Cdk5-deficient medulloblastoma cells." (PMID 30687086, 2018). "We analysed a medulloblastoma cell line, ONS-76, as a CNS-derived model system and generated its derivatives, R1 and R2 cells, which constitutively expressed each mouse IRF-1 and IRF-2 cDNA at high levels." (PMID 9649118, 1998). "Simultaneously, they found that inhibition of CDK5 activity can regulate the continuous expression of interferon regulatory factor 2 (IRF2) and interferon IRF2BP2 in medulloblastoma (MB) mouse model, decreasing PD-L1 expression and then eliminating immune evasion." (PMID 35006426, 2021).
ovarian carcinoma (3 papers, 2016 to 2020). A malignant neoplasm originating from the surface ovarian epithelium. "The network based approach identified two 7-gene functional interaction modules (31: DCLRE1A, EXO1, KIAA0101, KIN, PCNA, POLD3, POLD2; 35: DKK3, FABP3, IRF1, AIM2, GBP1, GBP2, IRF2) that are associated with prognosis of ovarian cancer patients." (PMID 27806724, 2016). "However, high expression of IRF-2 in ovarian cancer patients was reported to be associated with improved disease-free and overall survival." (PMID 28465494, 2017).
acute respiratory distress syndrome (2 papers, 2020 to 2021). Progressive and life-threatening pulmonary distress in the absence of an underlying pulmonary condition, usually following major trauma or surgery. "Additionally, XIST enhanced lipopolysaccharide- (LPS-) induced acute respiratory distress syndrome by upregulating the levels of interferon regulatory factor 2 by binding to miR-204." (PMID 34512861, 2021).
atherosclerosis (2 papers, 2016 to 2022). A disease characterized by the build-up of fatty material and calcium deposition in the arterial wall resulting in partial or complete occlusion of the arterial lumen. "Among IRF2 targets were the inhibitors of inflammation myocyte enhancer factor 2C (MEF2C) and annexin A1, (ANXA1, also known as lipocortin 1), which was recently shown to decrease atherosclerosis in a mouse model." (PMID 27068706, 2016). "In contrast, TNF, interferon regulatory factor 2 (IRF2) and interferon gamma (IFNG) were predicted to be inhibited and insulin activated in both datasets, and the computing of LARP1 activity was not possible in VAT samples from humans with atherosclerosis." (PMID 35737302, 2022).
colitis (2 papers, 2015 to 2020). Inflammation of the colon. "Here, using a dextran sodium sulfate (DSS)-induced colitis model, we explore the role of IRF2 in maintaining colonic epithelial stem cells (CoSCs)." (PMID 32901054, 2020). "Thus, IRF1 and IRF2 have the potential to be selective and potentially effective targets for the treatment of both experimental colitis and pediatric IBD." (PMID 26085826, 2015). "In this study, we found that deleting Irf2 specifically in the intestinal epithelium of mice reduced the number of CoSCs and severely impaired epithelial regeneration after the development of DSS-induced colitis." (PMID 32901054, 2020).
influenza (2 papers, 2011 to 2022). An acute viral infection of the respiratory tract, occurring in isolated cases, in epidemics, or in pandemics; it is caused by serologically different strains of viruses (influenzaviruses) designated A, B, and C, has a 3-day incubation period, and usually lasts for 3 to 10 days. "However, a specific role for IRF-2 in response to influenza infection has not been established." (PMID 22074594, 2011). "STAT1 and the JAK/STAT signaling pathway is known to be targeted by influenza virus, but IRF2 and IRF5 have not been demonstrated to play a role in response to influenza infection previously and thus represent novel predictions for further experimental investigation." (PMID 22074594, 2011).
latent infection (2 papers, 2011 to 2021). "Consistent with the repressive role of IRF2, IFNβ was significantly elevated during latent infection in IRF2-/- mice." (PMID 22114555, 2011). "In another study, IRF2 expression was induced during acute and latent infection." (PMID 34930359, 2021). "Thus, IRF2 binds the M2 ISRE during latent infection in the spleen." (PMID 22114555, 2011).
listeria infection (2 papers, 2013 to 2022). "Irf-2-deficient mice are highly susceptible to Listeria monocytogenes infection, which seems to be related to IRF-2's role in mediating the IFN-γ-induced oxidative burst that kills the pathogen inside intracellular compartments of macrophages." (PMID 24379524, 2013). "In contrast, monocytes from the listeria infection model expressed M1-related transcription factors (e.g., Irf2, Mndal, Ifi204) and showed higher expression of CD38, CD74, and CD86, as well as higher ROS production." (PMID 36010615, 2022).
neuroblastoma (2 papers, 2019 to 2022). Neuroblastoma (NB) is the most common solid, extracranial childhood tumor. "Another target of IRF1 and IRF2 that is implicated in neuroblastoma is Caspase-8 and its family member Caspase-7." (PMID 31178872, 2019). "For instance, IRF1 and IRF2 interact synergistically to suppress neuroblastoma by regulating apoptotic caspase-7/8 and MHC-I gene expression." (PMID 36498991, 2022). "Moreover, IRF2 was found to repress NF-κB induced MHC-I gene expression, involving more IRF family members in the low-MHC-I mediated Neuroblastoma disease progression." (PMID 31178872, 2019).
squamous cell carcinoma (2 papers, 2019 to 2023). A carcinoma arising from squamous epithelial cells. "Interestingly, several DM protein-coding genes, namely the LGI1, IRF2, and NRG1 genes, have been implicated in squamous cell carcinoma, which involves the same keratinocyte layer that is exclusively hijacked by HPV infection." (PMID 31892232, 2019).
Stroke (2 papers, 2013 to 2017). Sudden impairment of blood flow to a part of the brain due to occlusion or rupture of an artery to the brain. "Although a beneficial effect of IFNβ to limit stroke injury remains controversial, IFNβ is known to limit inflammatory cytokine expression via IRF2." (PMID 28769762, 2017).
systemic lupus erythematosus (2 papers, 2014 to 2018). An autoimmune multi-organ disease typically associated with vasculopathy and autoantibody production. "Limited and not very well-replicated studies have reported an association of IRF2 polymorphism with susceptibility to the autoimmune disease systemic lupus erythematosus (SLE)." (PMID 30515152, 2018). "Previous linkage and association studies in European-American populations suggested genetic role of IRF2 in systemic lupus erythematosus (SLE); however, this observation has not yet been confirmed." (PMID 25285625, 2014).
acute kidney injury (1 paper, 2021). Sudden and sustained deterioration of the kidney function characterized by decreased glomerular filtration rate, increased serum creatinine or oliguria. "Zhao and colleagues found that rs62341639 and rs62341657 polymorphism on chromosome 4 near the APOL1 regulator IRF2 and rs9617814 and rs10854554 polymorphism on chromosome 22 close to the acute kidney injury-related gene TBX1 were associated with AKI development but without genome-wide significance." (PMID 34300206, 2021).
breast tumors (1 paper, 2015). "In contrast, IRF2 is more frequently expressed in high-grade breast tumors, and rarely seen in normal breast tissue." (PMID 26460486, 2015).
endometriosis (1 paper, 2025). The growth of functional endometrial tissue in anatomic sites outside the uterine body. "Compared to normal human endometriosis cells, the expression of BAK1, CHMP2A, GPX4, and GSDMD was upregulated, whereas the expression of CHMP2B, IRF2, and TIRAP was negatively regulated in UCEC cells." (PMID 40535818, 2025).
ependymoma (1 paper, 2021). A WHO grade II, slow growing tumor of children and young adults, usually located intraventricularly. "By elucidating core transcriptional regulatory circuitries from the set of gained enhancers, we identified several key TFs, including RXRA, NFE2L2, IRF2, RELA, etc., involved in cell growth and migration, some of which were also revealed to have tumor-promoting functions in ependymoma and RCC25,26." (PMID 34294701, 2021).
glioblastoma (1 paper, 2021). The most malignant astrocytic tumor (WHO grade IV). "IRF2 transcript levels were also higher in glioblastoma than normal brain tissues in two datasets from TCGA (fold change = 3.705 and 2.448, respectively; p = 0.002 and 7.92E-9, respectively)." (PMID 33902005, 2021).
Hepatic fibrosis (1 paper, 2018). The presence of excessive fibrous connective tissue in the liver. "Recently, He et al55 found that transcription factor IRF2 could bind to the promoter of miR‐351 and inhibit its expression to regulate schistosomiasis hepatic fibrosis." (PMID 30091834, 2018).
major depressive disorder (1 paper, 2022). An episode of depression lasting two or more weeks without an intervening episode of mania. "For instance, the IRF2 targeting miRNA miR-221-3p has been found to be over-expressed in patients with the major depressive disorder compared with normal persons." (PMID 35572537, 2022).
MELAS (1 paper, 2023). "In IRF2 targets, which were significantly enriched in MELAS subjects, Polg mice, and Tfam± MEFs, USP18, TAP1, BST2, IFI35 were consistently increased." (PMID 37208779, 2023). "While these modules were not significant in MELAS patients, related viral sensing and IRF2 targets clusters were." (PMID 37208779, 2023).